MSI2 (musashi RNA binding protein 2)
Diseases named in the same sentence as MSI2 in open-access papers (continued):
Sharing a sentence is not in itself a finding about the gene and the disease.
tumor (continued). "Notably amplified regions included the KSR2, CANT1, MSI2 and MAP2K4 genes, all of which have been implicated in tumour progression, cell signalling, or regulation of proliferation." (PMID 40813389, 2025). "Although MSI2 overexpression in DLBCL indicates that MSI2 inhibitors may preferentially target tumor cells, future in vivo studies are essential to evaluate potential effects on normal tissues." (PMID 40843174, 2025). "Notably, the majority of lung tumors that formed in Msi2−/− KP mice were found to express Msi2, suggesting that the tumors that formed in Msi2−/− KP mice were escapers that re-expressed Msi2, underscoring the dependency on Msi2 signaling for tumor formation." (PMID 40047406, 2025). "Additionally, this dependency was conserved in human disease as inhibition of Msi2 impaired tumor growth in PDXs." (PMID 40047406, 2025). "Regarding tumor metabolism, MSI2 could increase the translation and stability of targeted proteins to alter amino acid metabolism and glycolipid metabolism processes." (PMID 38347600, 2024). "In addition, we further discovered that Jolkinolide B reduces the MSI2 expression, which can reverse Jolkinolide B-induced anti-tumor effects." (PMID 38630658, 2024). "Given its relevance to DNA damage repair and tumor development, similar to our study on MSI2, we found it intriguing and chose to delve deeper into understanding the relationship, functions, and mechanisms between MSI2 and RBM17." (PMID 38645664, 2024). "Collectively, this study suggests that MSI2 may ﻿improve the prognosis of CRC patients by reprogramming the tumor immune microenvironment (TIME) through HMGB1-mediated PTMs, which ﻿might be a novel therapeutic option for CRC immunotherapy." (PMID 38347600, 2024). "To investigate whether HMGB1 released from CRC tumor cells is responsible for MSI2-mediated immune activation in vitro and in vivo, we first treated stable SW620 and LOVO cells with Gly or DMSO for 24 h." (PMID 38347600, 2024). "Mice were monitored for tumor growth for 10 weeks whereupon we observed that tumor volumes were significantly larger in MSI2 overexpressing, Huh7 cell-derived tumors compared to the MSI2-silenced Huh7 mice recipients." (PMID 37117191, 2023). "Overexpression of MSI2 in TICs promoted their self-renewal and tumor-initiation properties." (PMID 37117191, 2023). "Our results suggest that MSI2 might play a key role in sustaining stemness and tumor cell survival, representing a possible novel target for therapeutic interventions in MCL." (PMID 36509891, 2023). "Addition of IL-6 to the CM from MSI2-depleted CAFs restored the EMT in NSCLC cells, in parallel with an observed rescue in NSCLC spreading impairment in 2D and 3D invasion assays, thus supporting secreted IL-6 as a key mediator of the tumor-promoting effects of CAFs mediated by MSI2 via EMT." (PMID 37941042, 2023). "To date, numerous studies have primarily focused on the functional role of MSI2 in tumor cells; however, its role in TME stromal cells is relatively unknown." (PMID 37941042, 2023). "Moreover, ex vivo bioluminescence analysis showed a significant decrease in tumor signals in the lungs of gMSI2 CAF group, indicating that MSI2-deficient CAFs inhibited NSCLC lung metastasis." (PMID 37941042, 2023). "We performed RIP-seq using anti-MSI2 antibody in tumor-initiating stem-like cells (TICs)." (PMID 37117191, 2023). "Smarcd3 deletion led to a greater significant loss (3-fold) in EpCAM+ tumor cells, and a 3.5-fold reduction in EpCAM+MSI2+ tumor stem cells in secondary transplants, suggesting that Smarcd3 deletion reduces the self-renewal capability of established tumor cells." (PMID 36653361, 2023). "HEL group, indicating that the subcutaneous tumor inoculated with MSI2-OE." (PMID 37149661, 2023). "MSI2 depletion or specific inhibition reduced colony formation, cell survival, leukemogenesis, self-renewal and proliferation followed by differentiation in several tumor cells." (PMID 36509891, 2023).
tumor (continued). "Based on these data, we hypothesized that MSI2 expression may provide a useful biomarker for tumor aggressiveness in CRC." (PMID 34237057, 2021). "Given our analysis of clinical specimens suggested a connection between MSI2 expression, E-cadherin/CDH1 expression, and tumor grade, particularly in tumor metastases, we analyzed whether MSI2 might directly regulate E-cadherin expression in CRC." (PMID 34237057, 2021). "Twenty days after xenografting, tumor weight was significantly reduced in the MSI2 knockout tumors." (PMID 35153752, 2021). "In a variety of tumours, knocking down MSI2 can inhibit invasion and EMT protein expression." (PMID 32606289, 2020). "MSI2 can regulate tumour progression through PTEN, Smad3, TGF-β, LRIG1 and others." (PMID 32606289, 2020). "Furthermore, the increasing expression of MSI2 with proximity to tumour, alongside its effects on β-catenin translocation, is consistent with the module-specific enrichment of components involved in formation of the β-catenin:TCF-transactivating complex." (PMID 29093438, 2017). "WB was performed to verify MSI2 silence in the tumor samples." (PMID 27092875, 2017). "It indicated that MSI2 also promoted tumor growth by up-regulating Ki-67 expression in vivo." (PMID 27092875, 2017). "Furthermore, 100% of the mice in the MDA-MB-231 (Scr-treated, MSI2-depleted) and Scr-treated clone #1 tumor-bearing groups exhibited tumor growth in the mammary fat pad; however, only 50% of the mice in the MSI2-depleted clone #1 tumor-bearing group exhibited discernable tumor growth." (PMID 39990676, 2025). "Interestingly, this analysis also showed that the role of Msi2 may extend to the regulation of processes crucial for tumor growth, such as metabolism and DNA repair, thus placing it upstream of multiple potent oncogenic signals." (PMID 40047406, 2025). "Furthermore, whether Msi2 is a dependency for tumor initiation or required for continued propagation, and which pathways are regulated by Msi2 to drive tumor growth, also remain unknown." (PMID 40047406, 2025). "Importantly, elevated MSI2 expression at an early tumor stage may predict worse outcomes in later tumors." (PMID 34237057, 2021). "We aimed to determine whether HMGA2 regulates tumour growth through MSI2." (PMID 31053152, 2019). "For instance, MSI2 is markedly up-regulated across multiple malignancies including PDAC and plays crucial roles in tumor initiation and progression through regulation of core oncogenic pathways." (PMID 41049614, 2025). "Recent evidence has increasingly shown that MSI2 plays a role in the progression of solid tumors by promoting CSC‐like characteristics and boosting tumor growth, spread, metastasis, and resistance to drugs." (PMID 38881674, 2024). "To validate the role of MSI2 and RBM17 in radioresistance, we constructed stable transgenic cell lines with knockdown of MSI2 and RBM17 and overexpressed another molecule in the knockdown cell line, and nude mice were tumor‐loaded subcutaneously." (PMID 38645664, 2024). "Our results demonstrate that circMALAT1 acts as a critical positive regulator in the control of tumor stemness and drug resistance of ESCC by binding to the CSC‐functional protein Musashi RNA Binding Protein 2 (MSI2)." (PMID 38881674, 2024). "Quantitative analysis of MSI2 and MYC staining showed that tumor regions of human HCC tissue sections had significantly higher levels of MYC and MSI2, which was consistent with TCGA data regarding MYC and MSI2 mRNA levels." (PMID 37117191, 2023). "Further, shRNA-mediated knockdown of Smarcd3 in MSI2+ KPf/fC cells almost completely blocked flank tumor growth in NOD-SCID mice in vivo, reducing growth rate by over 4-fold, and total tumor cell and MSI2+ tumor stem cell counts by 2.5 and 3.5-fold." (PMID 36653361, 2023). "The analysis of human tumor specimens for MSI2 correlated with MYC expression and MSI2 expression was elevated in late-stage HCC (stage III–IV)." (PMID 37117191, 2023).
tumor (continued). "The results revealed that tumor tissues had significantly higher expression of DDB2, MSI2, and RBM15 than the normal tissues." (PMID 35288483, 2022). "More importantly, in vivo xenograft assays also revealed that LIN28A-enhanced tumor growth and pulmonary localization were dependent on LIN28/MSI2-mediated YAP1 activation." (PMID 35102250, 2022). "One of the highly expressed transcription factors in Msi2-expressing CSCs is the nuclear hormone receptor RORγ, which controls both stemness and proto-oncogenic transcriptional programs and could be pharmacologically targeted to reduce tumour burden in human and murine models." (PMID 36088504, 2022). "To confirm the roles of MSI2, SNORD12B, and ZBTB4 in tumor growth in vivo, we subcutaneously injected GBM MSI2(−) cells, SNORD12B(−) cells, ZBTB4(+) cells, or a combination of the three cells to construct mouse xenograft models." (PMID 34047477, 2021). "Because our data suggested a potential relationship between MSI2 expression and tumor grade in CRC metastases, we investigated the expression of E-cadherin (CDH1), in relation to MSI2, in 28 randomly chosen patients with mCRC." (PMID 34237057, 2021). "Certainly, given the promising results of this study, our findings justify further exploration of MSI2 signaling mechanism and development of strategies of targeting MSI2 for use in EGFRmut NSCLC, and potentially other tumor types." (PMID 33723247, 2021). "MSI2 expression correlated with decreased progression free survival (PFS) and overall survival (OS), higher tumor grade, and right-side localization (p = 0.004) of tumors." (PMID 34237057, 2021). "HMGA2 knockdown regulates autophagy via MSI2-Beclin1 interactions to inhibit NF1 MPNST growth, revealing potential therapeutic targets for these untreatable tumours." (PMID 31053152, 2019). "In this study, we demonstrated that MSI2 was highly expressed in human HCC tissues and correlated with poor tumor differentiation, and poor prognosis." (PMID 31888685, 2019). "The difference in DNA methylation between RFS and n/RFS primary tumours was less considerable, although a statistically significant difference was observed for DAXX, P<0.0001; RXRA, P<0.01; C8orf46, P=0.01; NCOR2 and MSI2 (P<0.05; t-test) enhancer regions." (PMID 26169690, 2015). "The MSI2 expression levels in 903 tumor tissues and 103 adjacent normal tissues were significantly increased." (PMID 39990676, 2025). "(A) Schematic of the strategy used to measure the tumor sphere-forming capacity of Msi2-expressing and non-expressing cells in vitro." (PMID 40047406, 2025). "A-to-I editing of miR-3144-3p (3_A < G) by ADAR1 in liver cancer drastically shifts the target specificity of this miRNA, with the defective target of its canonical mRNA target Musashi RBP 2 (MSI2, an oncogene), whereas generating gain-of-function binding to SLC38A4 mRNA (a tumor suppressor)." (PMID 39126156, 2025). "Musashi‐2 (MSI2), an RNA‐binding protein (RBP), is upregulated in specific NSCLC tumor subgroups." (PMID 39969091, 2025). "For the non‐irradiated tumors, we found that knockdown of MSI2 and RBM17 could significantly inhibit tumor growth." (PMID 38645664, 2024). "We found that knockdown of either MSI2 or RBM17 had significant radiosensitizing effects, and MSI2 partially reversed the effect of knockdown of RBM17 on tumor radiosensitivity, while RBM17 significantly reversed the effect of knockdown of MSI2 on tumor sensitivity." (PMID 38645664, 2024). "Analysis of IHC staining results for MSI2, HSPB1, p-HSPB1(Ser78) and Ki67 showed that MSI2 knockout could reduce the expression of HSPB1, p-HSPB1(Ser78) and the tumor proliferation capacity in transgenic CAC mice." (PMID 38041016, 2023). "Western blot analyses confirmed the modulation of Adar1, Msi2, and Slc38a4 expression in the noncancerous liver tissues surrounding tumor masses." (PMID 36599932, 2023).
tumor (continued). "MSI2 binds the internal ribosome entry site (IRES)-containing oncogene mRNAs including MYC, JUN and VEGFA as well as HCV IRES to increase their synthesis and promote self-renewal and tumor-initiation at the post-transcriptional level." (PMID 37117191, 2023). "Taken together, both in vitro and in vivo studies strongly indicate the role of CAF MSI2 in promoting NSCLC metastasis without impacting tumor cell growth." (PMID 37941042, 2023). "Together, these results strongly indicate that MSI2 has no influence on NSCLC tumor growth in vivo, in agreement with the in vitro data on NSCLC cell growth." (PMID 37941042, 2023). "In contrast, in similar experiments performed in the KRAS-dependent A549 cell line, neither MSI2 depletion, erlotinib treatment, nor the combination significantly impaired tumor growth." (PMID 33723247, 2021). "Some work has suggested MSI2 regulation of genes governing EMT and aggressive tumor growth may be relevant in CRC." (PMID 34237057, 2021). "Moreover, it would be interesting to compare which transcripts Msi2 targets in different cellular contexts, including ESC, HSC and tumor cells." (PMID 22496868, 2012). "Moreover, MSI2 depletion inhibited lung metastasis in metastatic mouse models but did not affect proliferation or tumor size." (PMID 39990676, 2025). "MSI2 knockdown in clone #1 did not affect tumor size, indicating that MSI2 might not be related to cell proliferation in DEHP-exposed cells." (PMID 39990676, 2025). "In vivo experiments showed that the tumor volume and weight in the si-SOX2-OT#2 group were significantly decreased compared with the control group (all P < 0.05), and there were significant differences in miR-143-3p and MSI2 mRNA levels in tumor tissues (all P < 0.001)." (PMID 34322386, 2021). "However, no study has focused on the role of MSI2 in tumor iron death, particularly in CRC." (PMID 38041016, 2023). "Three days following the final dose of tamoxifen, lungs were dissociated and Msi2-expressing (GFP+) or non-expressing (GFP−) cells were isolated by FACS and then plated in a tumor sphere assay." (PMID 40047406, 2025). "Although the high level of MSI2 has been linked to high-grade NSCLC and metastatic staging in patients, which was validated in the present study, the expression of MSI2 and its functional role in TME stromal cells during tumor progression and metastasis have never been studied." (PMID 37941042, 2023). "In agreement with the in vitro data, co-injection of NSCLC cells with MSI2-depleted CAFs in a xenograft mouse model resulted in decreased local and distant metastatic spreads of NSCLC cells as compared to co-injection with control CAFs without affecting primary tumor growth." (PMID 37941042, 2023).
hematologic malignancies (10 papers, 2019 to 2026). "In context of hematologic malignancies, MSI2 is required for the development and progression of myeloid leukemias." (PMID 38234720, 2023). "MSI2 is extensively expressed in both solid and hematological malignancies." (PMID 37941042, 2023). "While the main focus of the work reported here is the role of MSI2 translocation in hematologic malignancies, this discovery may lay a foundation for defining the role MSI2 genetic lesions may play as oncogenes in other disease settings." (PMID 38234720, 2023). "Finally, recent findings pointed to MSI2 as a promising therapeutic target for solid and hematological malignancies." (PMID 37107676, 2023). "MSI2 regulates self-renewal and differentiation in ESC and HSCs, and is overexpressed in solid and hematological malignancies." (PMID 36509891, 2023).
blood cancer (3 papers, 2019 to 2026). "Musashi RNA-binding protein 2 (MSI-2) has been demonstrated to be involved in several solid and blood cancers, where its expression emerged to be higher than in normal tissues and correlate with the prognosis." (PMID 31878037, 2019). "The role of MSI2 expression in OSCC seems to be not so closely correlated with prognosis, as in other solid and blood tumors." (PMID 31878037, 2019).
infection (3 papers, 2012 to 2021). The state of being infected such as from the introduction of a foreign agent such as serum, vaccine, antigenic substance or organism. "A loss of MSI2 function negatively impacts a host's innate immune responses in response to infection by affecting hematopoietic cell homeostasis and thus leukocyte development in both humans and mice." (PMID 34409086, 2021). "Three days after infection with the lentiviral vectors, western blot analysis determined that MSI2 isoform 1 and isoform 2 were both substantially reduced and the reduction in MSI2 was verified at the RNA levels by RT-qPCR." (PMID 23667531, 2013). "Moreover, photomicrographs taken 7 days after infection demonstrated that cells in which MSI2 had been knocked down were flatter and larger, reminiscent of post-mitotic cells, when compared to the Scrambled control." (PMID 23667531, 2013).
neurodegenerative disease (2 papers, 2019 to 2020). A disorder of the central nervous system characterized by gradual and progressive loss of neural tissue and neurologic function. "To evaluate the different levels and distributions of MSI1 and MSI2 amongst varying neurodegenerative diseases, we co-stained AD, ALS, FTD, aged Control brains MSI1 and MSI2 with anti-tau oligomeric monoclonal antibody (TOMA-2)." (PMID 32855391, 2020).
cardiovascular diseases (1 paper, 2020). "Nevertheless, more in vivo and in vitro studies are needed to investigate the pathological meaning of MSI2-mediated redistribution of miR-301a-3p in cardiovascular diseases." (PMID 33553241, 2020).
MSI2 also shares sentences with these, for which no sentence is quoted: acute lymphoblastic leukemia (3 papers); Alzheimer disease (2); aneurysm (2); clear cell renal cell carcinoma (2); colon adenocarcinoma (2); esophageal cancer (2); frontotemporal dementia (2); Huntington disease (2); mantle cell lymphoma (2); neurological diseases (2); Parkinson disease (2); acute megakaryoblastic leukemia (1); acute promyelocytic leukemia (1); adenocarcinoma (1); age-related macular degeneration (1); anemia (1); autoimmune (1); breast invasive carcinoma (1); chronic leukemia (1); colon adenoma (1); colon polyps (1); colorectal adenocarcinoma (1); COVID-19 (1); diabetes nephropathy (1); diabetic retinopathy (1); diffuse large B-cell lymphoma (1); endometrial cancer (1); hemorrhage (1); lung disease (1); lymph node metastasis (1).
A further 19 diseases each share a sentence with MSI2 in 1 paper.